GK (glycerol kinase)
Diseases named in the same sentence as GK in open-access papers (continued):
Sharing a sentence is not in itself a finding about the gene and the disease.
infection (27 papers, 2013 to 2025). The state of being infected such as from the introduction of a foreign agent such as serum, vaccine, antigenic substance or organism. "Further, mutation of the key amino acids of gK affects viral axon terminal invasion and retrograde infection, so as to limit the retrograde labeling." (PMID 35012591, 2022). "Of note, lmo1538, encoding a glycerol kinase, was found to be upregulated after infection of epithelial cells, macrophages and splenocytes." (PMID 26579105, 2015). "However, gK deficiency abolishes viral egress, transneuronal transmission, and infection of H129-dgK-G4." (PMID 35012591, 2022). "Point mutations in gK represent, by far, the most frequent genetic mutations that produce the syncytial phenotype in which infected cells fuse extensively in early stages of infection." (PMID 34960625, 2021). "The expression level of GK in the resistant variety YC05–179 was increased and higher than that in the susceptible variety ROC22 after infection with S. scitamineum, which may corroborate the positive correlation between the expression level of GK and smut resistance in sugarcane varieties." (PMID 30658590, 2019). "DnCPV-23 infection can affect the expression of critical genes involved in energy metabolism, such as glycerol kinase-like (GK; Gene ID: LOC118276660) and trehalose transporter 1 (Tret1; Gene ID: LOC118271571, LOC118279019)." (PMID 40806613, 2025). "It was reported that recombinant HSV-1 coated with the gK protein from strain KOS dramatically decreased infection efficiency through the axon invasion than the virus coated with gK from strain McKrae." (PMID 35012591, 2022). "gK is related to viral egress, viral particles axonal transport, virus-induced cell fusion, as well as infection via axon invasion." (PMID 35012591, 2022). "At 16 hr post infection (PI), cells were fixed, permeabilized, and immunostained with anti-V5 (to detect gK) and anti-GM130 (to detect the Golgi complex)." (PMID 34352042, 2021). "The syncytial gK mutants of HSV-1 have been used in multiple studies to investigate the function of gK during infection." (PMID 33374862, 2020). "When gK is expressed outside the context of the infection, it localizes in the ER and the perinuclear space." (PMID 33374862, 2020). "Wild-type gK can also inhibit fusion that is triggered by other HSV-1 glycoproteins outside the context of the infection." (PMID 33374862, 2020). "Infection with CK177gK-HA revealed that gK localizes in cytoplasm, nuclear rim and even in nuclei by immunofluorescence using antibodies against HA." (PMID 31448105, 2019). "Following infection with CK177ΔUs3gK-HA, gK-HA signals are strongly enhanced in the cytoplasm (forming large clusters), at the nuclear rim and in nuclei." (PMID 31448105, 2019). "These glycoproteins (gB, gC, gD, gE, gG, gH, gI, gJ, gK, gL, gM, and gN) are the major inducers and targets of humoral and cell-mediated immune responses following infection." (PMID 30581441, 2018). "Following Ad‐GK infection, GK mRNA levels peaked on day 4 and then gradually reduced." (PMID 39418169, 2024). "The involvement of gK in nuclear egress was indicated by the surprising observations that overexpression of gK in stably transfected cells followed by infection of wild-type HSV resulted in extensive accumulation of enveloped virus particles in the perinuclear space." (PMID 34960625, 2021). "During infection, UL20 protein is required for gK transport to the surface, which is necessary for virus-induced cell fusion that is caused by syncytial mutations in either gB or gK (i.e., mutations in the gB and gK genes that allow for formation of syncytia)." (PMID 33374862, 2020). "However, infection of syncytial gK-transfected cells with a gK-null virus triggered expression of gK on the cell surface and cell fusion." (PMID 33374862, 2020).
infection (continued). "While we have focused mostly on similarities across alphaherpesvirus gK orthologs, our analyses also identify areas of rapid evolution that may contribute to differences in infection and pathogenesis across species." (PMID 31601827, 2019). "Since the success in GK knockdown depends upon the efficiency of adenoviral transduction, time-course studies were carried out in order to determine the time point at which there was a maximal infection rate." (PMID 28623340, 2017). "The VC2 virus contains the gKΔ31-68 deletion (37 aa; gK aa 31–68) in the amino terminus of gK that prevents the virus from entering into ganglionic neurons after infection via the ocular route, as well as a deletion of the amino-terminal 19 amino acids of the UL20 virus." (PMID 25350288, 2014). "Furthermore, gK was minimal throughout the infection course." (PMID 39195802, 2024). "Indeed, others have also observed gK incorporated into nuclear membranes in the context of wtHSV-1 infection suggesting that gK may also play a significant role in envelopment of wtHSV-1 at nuclear membranes." (PMID 31448105, 2019). "Furthermore, gK and pUL20 are also thought to be important determinants of virus-induced cell fusion, as many different mutations within gK or pUL20 give rise to syncytial variants of HSV-1, which cause extensive cell-cell fusion upon infection." (PMID 25746217, 2015). "Differences in the amino acid sequence of gK among different HSV-1 strains also affect the viral entry efficiency, especially the axon terminal invasion and retrograde infection in neurons." (PMID 35012591, 2022). "The expression levels of GK and PFKFB3 in the S. aureus group were higher than those of the mock infection group (p < 0.001, respectively)." (PMID 31093495, 2019). "Finally, UL54 could enhance or repress gK expression in early infection." (PMID 28432334, 2017). "Infection of mice with adenoviruses expressing Gk shRNA significantly reduced GK expression in the liver, but not in other tissues." (PMID 39418169, 2024). "Infection with CK177ΔUs3gK-HA, a similar mutant lacking Us3 but equipped with an epitope-tagged gK, also induced multiple folds and invaginations of nuclear membranes containing virions." (PMID 31448105, 2019). "Also, a similar study with Bovine herpes virus type 1 (BoHV-1), a member of the alphaherpes virus family, demonstrated that BoHV-1 gK and UL20 proteins function together in a manner similar to HSV-1 gK and UL20 in virus spread and infection." (PMID 30581441, 2018). "Syncytial variants of gK cause even higher levels of fusion than those of gB, regardless of the MOI used during infection." (PMID 29742155, 2018). "Further, role of other HSV-1 glycoproteins such as gK which is known to be involved in virus spread and alterations in viral receptor expression in the eye, needs to be investigated during HSV-1-liposome mixture mediated infection in zebrafish ocular model." (PMID 27446014, 2016). "Several HSV-1 envelope proteins have been shown to internalize from the cell surface in the absence of infection: gB and gE, the gK/pUL20 complex and as shown here, in the presence of gM and gK/pUL20, gD and gH/gL." (PMID 25746217, 2015). "This last experiment confirmed the differential expression of the three GK genes and further identified a potential involvement of GKII, but not the other genes, in the intensity of infection symptoms and, consequently, to the level of aggressiveness of the P. nicotianae strains." (PMID 35208735, 2022).
tumor (6 papers, 2011 to 2025). "It was reported that OncdSyn with mutations at gB and gK caused extensive virus-induced cell fusion in cell cultures, but the titer in tumor cells was a half log lower than that of the wild-type HSV-1 strain F." (PMID 21663640, 2011). "Further investigation was conducted on 11 ESCA samples and their matched adjacent non-tumor samples, which corroborated the higher expression of GK in ESCA tissues (p < 0.01), aligning with the TIMER database findings." (PMID 38365953, 2024). "The potential for GK to induce resistance to anti-tumor drugs in ESCA necessitates further study to understand its mechanism of action." (PMID 38365953, 2024). "To investigate the expression level of the glycerol kinase (GK) gene in tumor tissues, we first analyzed GK levels across various tumor types compared to normal tissues using the TIMER database." (PMID 38365953, 2024). "Our findings demonstrate that the addition of GK-1 to BMDCs loaded with MAGE-AX decreases the rate of tumor growth and increases the survival of mice and the expression of CD86 and IL-12 in the BMDCs, as well as the levels of CD8 IFNγ producing T cells." (PMID 25759825, 2014). "Notably, we observed a significant association between GK expression and the activity of T and B lymphocytes, indicating GK’s possible role in tumor immune infiltration." (PMID 38365953, 2024). "Moreover, we observed that tumors treated with GK-1 have fewer ATP synthase subunit levels, which compromises tumor cell respiration, demonstrated by the significant decrease in S3, P, and RC." (PMID 36670920, 2022). "Previous studies have highlighted GK’s multiple functions, providing insights into glycerol kinase's diverse protein functions, but have not explored its direct correlation with tumor pathogenesis or development." (PMID 38365953, 2024).
cancer (5 papers, 2016 to 2026). A tumor composed of atypical neoplastic, often pleomorphic cells that invade other tissues. "Changes in glyceroneogenesis and GK expression, both alternate sources of Gro3P to glycolysis, have been implicated in cancer." (PMID 40927981, 2026). "With respect to GK, cancer tissue expression of GK-5 (both mRNA and protein), as well as elevated exosomal GK-5 mRNA levels in plasma, were reported in patients with gefitinib-resistant compared to gefitinib-sensitive lung adenocarcinoma." (PMID 40927981, 2026). "Collectively, these analyses highlight a significant upregulation of GK in ESCA, indicating its potential role in this cancer's pathology." (PMID 38365953, 2024).
GK also shares sentences with these, for which no sentence is quoted: hyperlipidemia (3 papers); metabolic disorders (3); Glucose intolerance (2); Intellectual disability (2); alcoholic hepatitis (1); alcoholism (1); allergic asthma (1); breast tumors (1); candidiasis (1); colon cancer (1); cryptorchidism (1); eosinophilic esophagitis (1); esophageal squamous cell carcinoma (1); Fanconi anemia (1); fungal infections (1); gastric cancer (1); genetic disorder (1); glucose metabolic diseases (1); Hypokalemia (1); hypothyroidism (1); Kearns-Sayre syndrome (1); leukemia (1); liver disease (1); lung adenocarcinoma (1); lung squamous cell carcinoma (1); muscular dystrophy (1); pancreatitis (1); phospholipidosis (1); prediabetes (1); Primary amenorrhea (1).
A further 4 diseases each share a sentence with GK in 1 paper.